ZNF443 (zinc finger protein 443)
Description:
May be involved in transcriptional regulation.
Synonyms: ZK1
Tractability: PROTAC: ubiquitination databases record sites on it.
Gene: Protein-coding gene on chromosome 19 (12,429,706 to 12,441,021, reverse strand). Ensembl gene ENSG00000180855.
Subcellular location: Nucleus
Subcellular location (Human Protein Atlas): Nucleoplasm; Centriolar satellite
Pathways (Reactome):
Gene expression (Transcription): Generic Transcription Pathway
Gene Ontology:
Molecular function: DNA-binding transcription factor activity, RNA polymerase II-specific; RNA polymerase II transcription regulatory region sequence-specific DNA binding
Biological process: apoptotic process; regulation of transcription by RNA polymerase II; regulation of DNA-templated transcription
Cellular component: nucleus
Genetic constraint (gnomAD): Loss-of-function variants: 3 observed, 6.24 expected, observed/expected ratio (o/e) 0.48, 90% interval 0.22 to 1.24. That is too few expected variants to judge how well the gene tolerates losing a copy. Missense variants: 758 observed, 779.11 expected, observed/expected ratio (o/e) 0.97, 90% interval 0.92 to 1.03. Synonymous variants: 222 observed, 256.79 expected, observed/expected ratio (o/e) 0.86, 90% interval 0.77 to 0.97.
Homologues: Orthologues: chimpanzee ZNF443 (98% identical), rat Zfp617 (30% identical), mouse Zfp961 (29% identical). Paralogues in human: ZNF799 (89% identical), ZNF823 (70% identical), ZNF442 (68% identical), ZNF44 (68% identical), ZNF441 (60% identical), ZNF563 (53% identical), ZNF700 (52% identical), ZNF433 (51% identical), ZNF709 (50% identical), ZNF14 (48% identical), ZNF791 (46% identical), ZNF878 (43% identical), and 3 more.
Diseases named in the same sentence as ZNF443 in open-access papers:
ZNF443 is named in the same sentence as 1 disease in open-access papers, as found by Europe PMC text mining. Sharing a sentence is not in itself a finding about the gene and the disease.
ZNF443 shares sentences with these, for which no sentence is quoted: cancer (1 paper).